ENSG00000200999
Synonyms: LOC124900179
Gene: Small nucleolar RNA gene on chromosome 4 (26,702,309 to 26,702,388, forward strand). Ensembl gene ENSG00000200999.
Gene Ontology:
Biological process: RNA processing
Cellular component: nucleolus
Homologues: Orthologues: mouse Gm26224 (72% identical), rat LOC120096384 (69% identical), zebrafish snord74 (65% identical). Paralogues in human: SNORD74B (65% identical).